ZBTB48 (zinc finger and BTB domain containing 48)
Description:
Plays a critical role in transcriptional regulation and chromatin remodeling. Acts as a regulator of telomere length. Directly binds the telomeric double-stranded 5'-TTAGGG-3' repeat. Preferentially binds to telomeres that have a low concentration of shelterin complex and acts as a regulator of telomere length by initiating telomere trimming, a process that prevents the accumulation of aberrantly long telomeres. Also acts as a transcription regulator that binds to promoter regions. Regulates expression of a small subset of genes, including MTFP1. Acts as a negative regulator of cell proliferation by specifically activating expression of ARF, a tumor suppressor isoform of CDKN2A. Acts as a transcription regulator of CIITA, the major factor regulating MHC class II gene expression. In addition, regulates cellular m6A/m6Am methylation on RNA by facilitating the recruitment of the RNA demethylase, FTO, to target mRNAs.
Synonyms: hKR3; TZAP; ZNF855; pp9964
Tractability: PROTAC: UniProt records ubiquitination sites on it; ubiquitination databases record sites on it.
Gene: Protein-coding gene on chromosome 1 (6,579,994 to 6,589,280, forward strand). Ensembl gene ENSG00000204859.
Subcellular location: Nucleus; Chromosome, telomere
Subcellular location (Human Protein Atlas): Nucleoplasm; Cytosol
Gene Ontology:
Molecular function: double-stranded telomeric DNA binding; identical protein binding; protein binding; RNA binding; transcription cis-regulatory region binding; zinc ion binding; DNA-binding transcription factor activity; RNA polymerase II cis-regulatory region sequence-specific DNA binding; sequence-specific DNA binding
Biological process: positive regulation of DNA-templated transcription; regulation of RNA metabolic process; telomere maintenance via telomere lengthening; regulation of transcription by RNA polymerase II
Cellular component: chromosome, telomeric region; nucleoplasm; nucleus; chromosome
Genetic constraint (gnomAD): Loss-of-function variants: 38 observed, 67.41 expected, observed/expected ratio (o/e) 0.56, 90% interval 0.43 to 0.74. The synonymous counts are far from expectation, so gnomAD's model fits this gene poorly and the ratio says little. Missense variants: 828 observed, 915.4 expected, observed/expected ratio (o/e) 0.9, 90% interval 0.85 to 0.96. Synonymous variants: 442 observed, 366.71 expected, observed/expected ratio (o/e) 1.21, 90% interval 1.11 to 1.3.
Homologues: Orthologues: chimpanzee ZBTB48 (99% identical), dog ZBTB48 (94% identical), guinea pig ZBTB48 (93% identical), macaque ZBTB48 (92% identical), rabbit ZBTB48 (92% identical), mouse Zbtb48 (91% identical), rat Zbtb48 (90% identical), pig ZBTB48 (88% identical), tropical clawed frog zbtb48 (61% identical), zebrafish zbtb48 (52% identical). Paralogues in human: ZNF160 (20% identical), ZNF84 (20% identical), ZBTB24 (20% identical), ZNF91 (19% identical), ZNF574 (19% identical), ZNF594 (19% identical), CTCF (19% identical), ZNF845 (19% identical), ZNF107 (19% identical), ZNF99 (19% identical), ZNF420 (18% identical), ZNF142 (18% identical), and 24 more.
Diseases named in the same sentence as ZBTB48 in open-access papers:
ZBTB48 is named in the same sentence as 37 diseases in open-access papers, as found by Europe PMC text mining. Sharing a sentence is not in itself a finding about the gene and the disease. The quoted sentences say what the papers report.
colorectal cancer (5 papers, 2020 to 2024). A primary or metastatic malignant neoplasm that affects the colon or rectum. "Previous researches have suggested that ZBTB48 has an auxo-action for progression colorectal cancer, and cervical cancer, and high expression of ZBTB48 is associated with poor prognosis in patients." (PMID 37723588, 2023). "ZBTB48 ablation also accelerates growth of HCT-116 colorectal cancer cells and modulates FTO-dependent regulation of Metastasis-associated protein 1 (MTA1) transcripts by controlling the binding to MTA1 mRNA of the m6A reader IGF2BP2." (PMID 39300486, 2024). "We have found that ZBTB48 expression inhibits the growth of colorectal cancer-derived HCT-116 cells." (PMID 39300486, 2024).
glioblastoma (2 papers, 2023 to 2025). The most malignant astrocytic tumor (WHO grade IV). "Additionally, IGF2BP3 is involved in the initiation of a circRNF10/ZBTB48/IGF2BP3 positive feedback loop in gliomas, leading to reduced Fe2+ accumulation and activation of ferroptosis defense mechanisms, which promotes glioblastoma (GBM) progression." (PMID 40271153, 2025). "However, the transcriptional regulation function of ZBTB48 has not been reported, and the mechanism of its action in glioblastoma remains to be further studied and explored." (PMID 37723588, 2023).
glioma (2 papers, 2023 to 2024). A benign or malignant brain and spinal cord tumor that arises from glial cells (astrocytes, oligodendrocytes, ependymal cells). "In this study, bioinformatics exploration based on TCGA and CGGA databases revealed a significant upregulation of ZBTB48 expression in high-grade gliomas, while a significant enrichment of ferroptosis pathway was observed in the ZBTB48 low-expression group." (PMID 37723588, 2023). "These bioinformatics analysis results signified that ZBTB48 upregulation is related to poor prognosis in glioma patients." (PMID 37723588, 2023). "ZBTB48 promotes the malignant progression of gliomas by inducing GSCs to evade ferroptosis." (PMID 39039049, 2024). "In addition, considering the specificity of the ZBTB48 gene locus, which involves the important molecular pathological feature of chromosomal 1p19q co-deletion in gliomas, we also observed a significant downregulation of ZBTB48 in the 1p19q co-deletion group." (PMID 37723588, 2023). "Besides, we further performed GSEA of the relationship between ZBTB48 and ferroptosis based on the TCGA-glioma and CGGA datasets." (PMID 37723588, 2023). "Since the discovered mutual interaction relationship between circRNF10 and ZBTB48 and their oncogenic and ferroptosis-defending role in glioma, we further evaluated whether ZBTB48 can serve as a pivotal downstream factor for circRNF10 against ferroptosis in GBM." (PMID 37723588, 2023). "Although our study has clarified the ubiquitination-mediated regulation of ZBTB48 by circRNF10, the biological function of ZBTB48 in glioma has not been reported." (PMID 37723588, 2023). "As there is no reported research on the regulatory function of ZBTB48 in ferroptosis, we conducted correlation analysis between ZBTB48 and ferroptosis-related genes in the CGGA and TCGA-glioma databases." (PMID 37723588, 2023).
cancer (15 papers, 2017 to 2025). A tumor composed of atypical neoplastic, often pleomorphic cells that invade other tissues. "In human cancer cells, ZBTB48 knockout strongly downregulated mitochondrial fission process 1 (MTFP1), mirroring the mitochondrial matrix reorganization phenotype of MTFP1 depletion." (PMID 39987415, 2025). "Conversely, the overexpression of ZBTB48 in human U2OS cancer cells maintaining telomere length via the alternative lengthening of telomere (ALT) pathway results in telomere shortening." (PMID 39987415, 2025). "Knockout of ZBTB48 in telomerase-positive human HeLa cancer cells and mouse embryonic stem cells results in telomere elongation." (PMID 39987415, 2025). "Interestingly, ZBTB48 has been localized to chromosome 1p36, a region that is commonly rearranged or deleted in many cancers." (PMID 39300486, 2024). "Therefore, ZBTB48 may act as a primary role in the pathogenesis of cancer." (PMID 37723588, 2023). "It was found in previous studies that ZBTB48 and ZBTB10 were involved in the progression of different cancers." (PMID 36098743, 2022). "ZBTB48 is found at telomeres of human cancer cells regardless of the mode of telomere maintenance and it acts as a negative regulator of telomere length." (PMID 28500257, 2017).
tumor (5 papers, 2017 to 2024). "Considering the multifunctional nature of ZBTB48, the underlying mechanism of ZBTB48-mediated growth inhibition and/or its potential role as a tumor suppressor is likely complex." (PMID 39300486, 2024). "Strikingly, the transcriptional regulation of IGF2BP3 by ZBTB48 leads to the formation of a positive feedback loop that continuously activates and strengthens the tumor-initiating potential of GSCs." (PMID 37723588, 2023). "Although ZBTB48 has been suggested to function as a tumor suppressor, its precise function in tumor cells remains unknown." (PMID 39300486, 2024). "We next investigated whether circRNF10/ZBTB48/ IGF2BP3 feedback loop impacts GBM tumor burden in vivo." (PMID 37723588, 2023). "In comparison, Fer-1 treatment group disrupted the survival benefit originating from circRNF10 knockdown, while the upregulation of ZBTB48 or HSPB1 completely abrogated the tumor suppressor effect mediated by circRNF10 knockdown, significantly reducing the survival time of mice." (PMID 37723588, 2023). "The positive feedback feature in GSCs mediated by the interaction among circRNF10, ZBTB48, with IGF2BP3 was morphologically identified by immunohistochemical staining of orthotopic xenograft tumor specimens." (PMID 37723588, 2023).
ZBTB48 also shares sentences with these, for which no sentence is quoted: breast carcinoma (5 papers); cervical cancer (3); colon carcinoma (2); hepatocellular carcinoma (2); leiomyoma (2); leukaemia (2); lung carcinoma (2); melanoma (2); Merkel cell carcinoma (2); neuroblastoma (2); pheochromocytoma (2); adenocarcinoma (1); age (1); B hepatitis infection (1); carditis (1); cervical squamous cell carcinoma (1); colon (1); colon adenocarcinoma (1); endocervical adenocarcinoma (1); esophageal cancer (1); head and neck cancer (1); hepatitis C infection (1); Impaired glucose tolerance (1); lung adenocarcinoma (1); nasopharyngeal carcinoma (1); non-small cell lung carcinoma (1); osteoporosis (1); pancreatic adenocarcinoma (1); pancreatic cancers (1); rectal cancer (1).
A further 2 diseases each share a sentence with ZBTB48 in 1 paper.